IGF1 (insulin like growth factor 1)
Diseases named in the same sentence as IGF1 in open-access papers (continued):
Sharing a sentence is not in itself a finding about the gene and the disease.
breast cancer (continued). "However, this is an early report and whether the absence of the IGF1 19-repeat allele could be used as an additional marker to improve risk estimates for early-onset breast cancer during genetic counselling warrants confirmation in a larger cohort." (PMID 15756256, 2005). "Insulin-like growth factor 1 (IGF1) is a potent inducer of mitosis and has been shown to synergize with oestrogen in stimulating the growth of human breast cancer in vitro." (PMID 9413957, 1997). "The bioavailability of IGF1 to the tissues is modulated by IGF-binding proteins (IGFBPs), and higher circulating levels of IGF1 and lower levels of IGFBP3 have been reported in breast cancer patients." (PMID 9413957, 1997). "Mean serum levels of insulin-like growth factor 1 (IGF-1), which is a growth factor for breast cancer, significantly decreased on therapy, and this decline was significantly higher in responders than in patients with SD or progression." (PMID 7710954, 1995). "OR5H2 could regulate endometrial cancer cell proliferation by interacting with the IGF1 signaling pathway, and OR5B21 drove breast cancer metastasis." (PMID 40523880, 2025). "Notably, IGF1 + CAF expressed all PDAC iCAF markers suggesting this phenotype represented the iCAF described in PDAC (and breast cancer) studies." (PMID 39757146, 2025). "Additionally, EB1089 inhibited the insulin-like growth factor 1 (IGF-1) signaling pathway, thereby inducing apoptosis in breast cancer cells." (PMID 40278307, 2025). "Although there is a strong biological rationale for a link between GH/IGF-1 excess and breast cancer, current clinical studies have not shown a clear or consistently increased risk in patients with acromegaly." (PMID 41293738, 2025). "Finally, insulin-like growth factor 1 (IGF-1), also called somatomedin C, binds to the IGF-1R receptor and triggers an anti-apoptotic cascade that contributes to breast cancer development, prognosis, and metastasis." (PMID 39272802, 2024). "In women with newly diagnosed breast cancer without diabetes, adding metformin to adjuvant therapy has been shown to decrease IGF-1, ratio of IGF-1 to IGFBP-3, insulin, fasting blood glucose, and HOMA-IR." (PMID 38543182, 2024). "The role of IGF-1 is mediated by IGF-1R, which is overexpressed in breast cancer." (PMID 36755926, 2023). "Augmented mortality rate in breast cancer-afflicted patients with pre-existent metabolic disorders like obesity and diabetes, via impaired IGF-1 cues acting via S100A7/RAGE pathway, thereby promoting cancer-related angiogenesis in breast cancer micro-milieu, has been reported." (PMID 37970208, 2023). "Insulin may cross-bind to insulin-like growth factor-I (IGF-1) receptors on breast cells, and downstream signaling pathways provide proliferation stimuli to breast cancer cells." (PMID 37467012, 2023). "In ERα-negative breast cancer, adiponectin inhibited IGF-1-induced cell migration, whereas in ERα-positive breast cancer, low concentrations of adiponectin promoted IGF-1R phosphorylation and thus enhanced IGF-1/IGF-1R signaling." (PMID 36755926, 2023). "Recent research has revealed that exercise may significantly exhibit decreased post-operative IGF-1, CRP, TNFα, and Il-6 levels in adult and older adult women with breast cancer." (PMID 37958310, 2023). "Our results suggest that CR may diminish IGF1/IGF1R signaling in two ways: by reducing circulating ligand, and by repressing Igf1r expression in a miR-15b-dependent manner in vivo (mammary tumors)." (PMID 37686596, 2023). "Although our study identified possible pathological roles for IGF1, ESR1, and CXCL12 in breast cancer and a potential synergistic effect of formononetin with immune checkpoint inhibitors in breast cancer immunotherapy, the limitation of this study is that it is only a data analysis-based prediction." (PMID 35463082, 2022).
breast cancer (continued). "Energy homeostasis genes play an important role in carcinogenesis and their interactions with the serum concentrations of IGF-1 and IGFBP-3 on the risk of breast cancer have not yet been investigated." (PMID 35115550, 2022). "In conclusion, our findings predict that IGF1, ESR1, and CXCL12 may be effective targets of formononetin as a therapeutic for breast cancer." (PMID 35463082, 2022). "We replicated previous findings by corroborating the breast cancer liability-increasing effects of testosterone, HDL cholesterol, and IGF-1 and generated the novel hypothesis that ALP is potentially liability-decreasing." (PMID 36424572, 2022). "Therefore, we considered IGF1, LEP, ADIPOQ, NR3C1, and PPARG as potential predictors for the poor prognosis of patients with breast cancer." (PMID 35317079, 2022). "Extracellular vesicles of insulin-like growth factor-1 (IGF-1), which is a crucial regulatory factor of mammary glands, promote the downregulation of CDH1 and upregulation of vimentin, N-cadherin, and MMP-9 in MDA-MB-231 breast cancer cells." (PMID 35464064, 2022). "After adjusting for BMI and alcohol in MVMR, genetically predicted HDL cholesterol, ALP, testosterone, triglycerides, IGF-1, and apoA had significant direct effects on overall breast cancer liability, while aspartate aminotransferase did not." (PMID 36424572, 2022). "IGF-1, produced by adipocytes, binds to IGFI on cancer cells and endorses cancer cell proliferation through PI3K/AKT and MAPK systems, whereas inhibition of IGF-1R abolishes the tumor promoting effect of adipocytes on breast cancer cells." (PMID 36077676, 2022). "In addition, we found that high expression of PRCP correlates with increased expression of IGF1/NRG1 and their target genes and earlier recurrence of endocrine treated ER+ breast cancer patients." (PMID 36332175, 2022). "IGF-1 system, consisting of IGF1, IGF-binding proteins (IGFBPs), and IGF1R, acts as one of the most upstream signaling pathways to regulate various pathophysiological processes during tumorigenesis including breast cancer." (PMID 36042202, 2022). "Therefore, this meta-analysis will focus on the effects of exercise on IL-6, IL-10, IL-1β, CRP, TNF-α, IGF-1 and IGFBP-3 levels in breast cancer patients." (PMID 36482346, 2022). "IGF-1 can induce the production of VEGF-C, a key pro-lymphangiogenic factor that stimulates lymphatic endothelial cell proliferation and migration and has been shown to promote breast cancer metastasis." (PMID 36556357, 2022). "Exercise reduces the postoperative levels of IGF-1, IL-6, CRP, IL-10 and TNF-α among patients with breast cancer, which may have a significant impact on inhibiting breast cancer recurrence and improving its prognosis." (PMID 36482346, 2022). "In addition, IGF-1 enhances IRS-2 phosphorylation to a greater degree than IRS-1 in metastatic mammary tumor cells, and knockdown of IRS-2 expression reduces IGF-mediated motility in vitro." (PMID 36556357, 2022). "Notably, three of these genes, including IGF1, PTGS2, and FGF1, were significantly related to breast cancer patient outcomes, thus further verifying their potential roles as prognostic biomarkers." (PMID 36035177, 2022). "IGF-1 has been shown to upregulate the expression of MMP-9 and uPA, as well as MMP-9 activity, in breast carcinoma cells, though this regulation may be cell-type specific." (PMID 36556357, 2022). "Furthermore, cancer-associated fibroblasts drive the selection of bone-metastatic breast cancer cells by selecting highly CXCL12- and IGF-1-responsive cells with an Src-dependent sensitivity for CXCL12- and IGF-1-mediated AKT activation." (PMID 34064589, 2021). "The FMD-dependent reduction in blood insulin, IGF-1 and leptin, which consequently leads to the inhibition of the PI3K/AKT, mTOR pathways, can also enhance the efficacy of estrogen therapies against estrogen receptor positive (ER+) breast cancer." (PMID 34572814, 2021).
breast cancer (continued). "A functional interaction between the IGF1R and CXCR4 was documented in breast cancer cell lines where CXCR4 and IGF1R directly interacted at the cell membrane, thereby inducing IGF1-evoked CXCR4 transactivation and cell migration independently of its cognate ligand CXCL12." (PMID 34440844, 2021). "In this work, we only focused on revealing how IGF1 and Ins stimulations exert different responses in breast cancer cells and not focused on the isoform specificity." (PMID 34191793, 2021). "Higher GHR, IGF-1, and IGF-1R expression are observed on breast cancer cells in humans." (PMID 34530525, 2021). "IGF1, for example, induces the expression of DDR1 in breast cancer cells." (PMID 33670586, 2021). "Our analysis revealed that a high expression of IGF-1 or IGF-1R (or both) does not affect the OS or DFS rates in patients with ER/PR-positive and HER2-negative breast cancer subtype, but it associates with a reduced DFS rate in TNBC patients." (PMID 32325700, 2020). "Similar results were obtained when breast cancer cells were treated with EGF, PDGF and IGF-1." (PMID 33203880, 2020). "IGF1 and IGF2 are overexpressed in PIK3CA-mutant breast cancer, which may activate IGF-IR signaling." (PMID 32493414, 2020). "Chemerin treatment inhibited nuclear β-catenin levels in breast cancer cells stimulated with or without TGF-β or IGF-1." (PMID 32325994, 2020). "No other significant associations with all-cause mortality, breast cancer-specific mortality, and breast cancer recurrence were observed for IGFBP3, IGF1/IGFBP3 ratio, insulin, and C-peptide." (PMID 32974138, 2020). "However, the specific mechanism of IGF‐1 and IGF‐1R regulating breast cancer angiogenesis requires further investigation yet." (PMID 32548873, 2020). "As recently published, insulin and insulin-like growth factor-1 (IGF1) activates several pro-mitogenic and pro-angiogenic signaling mechanisms and thus support pathogenesis and the progression of several cancers, including breast cancers." (PMID 32883003, 2020). "In addition, although the lack of a significant association between IGF1 and breast cancer recurrence was not in discordance with previous studies, there may be possible confounding factors that influence the observations, which deserve future clinical validations." (PMID 32974138, 2020). "The human breast cancer PCR array detected significantly increased expression of SLIT2 (slit guidance ligand 2) and decreased expression of IGF1 (insulin-like growth factor 1) and TWIST1 (twist family BHLH transcription factor 1) with 3-fold changes in the expression levels." (PMID 32565805, 2020). "The authors found that the expression of PD-1, PD-L1, and gene sets related to SRC, IGF1, and β-catenin were higher compared with non-parous breast cancer females." (PMID 33425733, 2020). "For example, both lung and breast cancer cell lines and patient tumors eventually evade mTOR inhibition after exposure to the rapamycin derivative RAD001 by increasing AKT phosphorylation through the upregulation of IGF-1 signaling." (PMID 32587773, 2020). "In line with this, lowering the serum GH and/or IGF1 by somatostatin analogs does not always have antitumor effects in clinical studies in breast cancer." (PMID 33260481, 2020). "In ER/PR-positive and HER2-negative breast cancer patients, the overall and disease-free survival rates did not evidence significant differences between high and low IGF-1/IGF-1R expression groups." (PMID 32325700, 2020). "Together this data indicates that BCATc regulates TNBC cell proliferation, migration and invasion through the IGF-1/insulin PI3K/Akt pathway, culminating in the upregulation of FOXO3a and Nrf2, pointing to a novel therapeutic target for breast cancer treatment." (PMID 32523652, 2020).
breast cancer (continued). "In accord with these results, breast cancer gene array profiling indicated that elevated expression of KLF4 in both MCF10A and MCF7 breast cancer cell lines upregulates transcription of several oncogenes and cell cycle activators such as MAPK, EGF/EGFR, IGF1, CYCLIN D2, CDK1, and CYCLIN E1." (PMID 30613353, 2018). "Experimental evidence in breast cancer and other cell lines suggests that steroids and growth factor signaling pathways such as EGF and IGF-1 have synergistic effects in inducing cell proliferation and that cross-talk between these pathways is important in estrogen action." (PMID 30400783, 2018). "Finally, its role on crosstalk between ERα and IGF‐1/AKT/mTOR pathway was confirmed, convincing us that CPT should be a potential agent for prospective application in a tamoxifen‐resistant breast cancer." (PMID 28272775, 2017). "Furthermore, IGF1/IGF1R signaling, which has angiogenic effects, has been shown to activate GPER in breast cancer cells." (PMID 29212519, 2017). "We hypothesized that obesity will increase liver steatosis and DHEA treatment will protect against liver steatosis by reducing body weight gain and modulating serum IGF-1 and IGFBP-3 levels in breast cancer model." (PMID 28335515, 2017). "As CPT could block ERα‐mediated IGF‐1/AKT/mTOR pathway, it needs to be clarified whether CPT could inhibit tamoxifen‐resistant breast cancer." (PMID 28272775, 2017). "Moreover, downregulation of PKM2 or β-catenin abrogated the IGF-1-induced miR-152 expression, suggesting that miR-152 was involved in a new IGF-1-mediated miR-152/PKM2/β-catenin regulatory circuit in breast cancer." (PMID 29162853, 2017). "IGF‐1 functions to protect breast cancer cells from apoptosis and induces survival 28, suggesting that locally synthesized IGF‐1 influences the growth of human breast cancer cells." (PMID 27734632, 2016). "In human breast cancer cell line MDA-MB-231, IGF-1 can regulate the secretion of VEGF-C by stimulating the MAPK/ERR1/2 signaling pathway, and the application of ERK1/2 inhibitors can block the effect of IGF-1 on VEGF-C secretion." (PMID 26911617, 2016). "An early case–control study conducted in 1993 demonstrated that circulating levels of IGF‐1 were higher in women with breast cancer compared to women without breast cancer." (PMID 27734632, 2016). "The contribution of the Grb2/Ras/MAP-kinase pathway to the protection by IGF-1 of oestrogen-responsive breast cancer cells from anoikis was tested with U0126 which is a non-competitive inhibitor of MEK1 and MEK2 that prevents activation of ERK1 and ERK2." (PMID 26801096, 2016). "Although circulating levels of insulin, IGF-1, GH and LEP in relation to breast cancer have been well studied, less is known about how germline variation in the insulin, IGF, GH, and LEP signaling pathways may affect risk of breast cancer." (PMID 27942580, 2016). "Autocrine produced hGH and hPRL could presumably also exert IGF1 and IGF2 independent oncogenic effects in HCC as has been previously reported for mammary carcinoma cells." (PMID 27102295, 2016). "Across all cases, overall survival and breast cancer-specific survival, unadjusted for confounders, did not vary by expression of IGF1, IGF1R, IGFBP2, or IGFBP3." (PMID 25619494, 2015). "Similar inhibition has been reported for other tissues and cells, such as AKT-induced phosphorylation of Raf-1 at Ser259 by insulin-like growth factor 1 in MCF-7, a human breast cancer cell line and by platelet-derived growth factor in vascular smooth muscle cells." (PMID 26442853, 2015). "Future studies should focus on clarification of the paracrine role of IGF-1, in establishment and progression of breast carcinoma, via in vivo models specifically overexpressing or lacking IGF-1 in stroma." (PMID 25743390, 2015).
breast cancer (continued). "High expression of insulin-like growth factor 1 receptor (IGF1R) and its two ligands, insulin-like growth factor 1 (IGF1) and insulin-like growth factor 2 (IGF2) have been demonstrated in OS, as well as many other cancers including rhabdomyosarcoma, breast cancer, prostate cancer, and colon cancer." (PMID 25170759, 2014). "IGF1 and IGF1R have been reported to play roles in the early transformation of mammary cells, induction of mammary epithelial hyperplasia in a transgenic mouse model, and breast cancer cell growth cells." (PMID 24392142, 2014). "More direct evidence from in vitro cell line studies indicated that IGF-1, insulin and estradiol induced the expression of leptin and OBR mRNA in the MCF-7 breast cancer cell line, while in MDA-MB-231 cells, leptin and OBR mRNA expression was induced by insulin or hypoxia." (PMID 23425972, 2013). "IGF-1 and IGF-2 signal through specific cell surface tyrosine kinase receptors, IGF-1 receptor (IGF-1R) and insulin receptor isoform A (IR-A)), that are highly expressed on human ER expressing breast cancer cells." (PMID 24171117, 2013). "Experimental Design: To test our hypothesis we assessed the inhibitory effect of protein diet restriction on prostate and breast cancer growth, serum PSA and IGF-1 concentrations, mTOR activity and epigenetic markers, by using human xenograft cancer models." (PMID 24353195, 2013). "Lycopene treatment of MCF-7 mammary cancer cells has been shown to slow down IGF-1-stimulated cell cycle progression, which was not accompanied by either apoptotic or necrotic cell death." (PMID 22418926, 2012). "Furthermore, studies indicate that glargine induced MCF-7 breast cancer cell proliferation to a significant level compared to the MCF-10 cells, but the stimulation was less compared to IGF-1." (PMID 21773024, 2011). "In this study we look at the effects of both IGF-1 stimulation, and increased latent TGF-β1 levels, on MCF-7 breast cancer cells to see if these proteins may work in conjunction to alter cellular morphology and increase the invasive potential of these cells." (PMID 21535875, 2011). "Laboratory studies have shown that oestrogen increases IGF receptor levels in breast-cancer cells, whereas in oestrogen-receptor-negative breast-cancer cells the levels of IGF1 receptor are decreased, and IGF1 is non-mitogenic." (PMID 20472501, 2010). "The documentation of higher cord blood levels of IGF-1, a principal growth hormone that does not cross the placenta, among Caucasian than in Asian newborns is concordant with breast cancer incidence in these populations." (PMID 19417744, 2009). "In summary, the impact of genetic variation in IGF1 and IGFBP3 on circulating IGF levels does not appear to substantially influence breast cancer risk substantially among primarily Caucasian postmenopausal women." (PMID 18596909, 2008). "Arnqvist and coworkers explored translation inhibition in MCF-7 breast cancer cells following cycloheximide, puromycin or emetine exposure in the presence and absence of Insulin-like Growth Factor1 (IGF-1)." (PMID 18431497, 2008). "Age at breast cancer diagnosis was not significantly influenced by multiparity in women with the IGF1+19 genotype (P=0.33)." (PMID 17311016, 2007). "The interaction between the IGF1-19/-19 genotype and multiparity on the age at breast cancer diagnosis has to our knowledge not been reported previously." (PMID 17311016, 2007). "The presence of IGF-1 immunoreactivity in breast cancer epithelial cells indicates a lower degree of malignancy than the lack of IGF1." (PMID 17092354, 2006). "As for postmenopausal breast cancer, neither the levels of circulating IGF-1 (Jernström and Barrett-Connor, 1999) nor the IGF1 genotype appear to affect the risk." (PMID 15756256, 2005).